NUAK2 (NUAK family kinase 2)
Diseases named in the same sentence as NUAK2 in open-access papers (continued):
Sharing a sentence is not in itself a finding about the gene and the disease.
glioblastoma (4 papers, 2018 to 2025). The most malignant astrocytic tumor (WHO grade IV). "In this study, we find that NUAK2 is a fetal oncogene whose expression is low in juvenile and adult brains, but high in developing brains and glioblastoma patients." (PMID 40770117, 2025). "NUAK2 was found to be re-expressed in glioblastoma and function as a fetal oncogene that promotes tumor growth and migration." (PMID 40770117, 2025). "In the A172 glioblastoma cell line, transient transfection of miRNA-143 downregulated NUAK2 expression which in turn reduced the proliferation, migration, and invasion potential of these cell lines." (PMID 34685740, 2021). "To determine whether NUAK2 is essential for promoting glioblastoma cell growth, we used a CRISPR-Cas9 system to silence NUAK2 in U251 cells, which express relatively higher levels of NUAK2 expression compared to the other three glioma cell lines." (PMID 40770117, 2025). "In both glioblastoma and cancer stem cells, downregulation of NUAK2 by micro-RNA could inhibit PI3k; thus, leading to downregulation of cyclin D1 and upregulation of p27." (PMID 39071701, 2024). "Additionally, NUAK2 has been found upregulated in different glioblastoma tumors in comparison with their normal counterparts." (PMID 34685740, 2021). "In addition, NUAK2 is involved in the development of glioblastoma via regulating the expression of cancer stem cell-related genes, and it promotes the cell cycle entry in the glioblastoma cells." (PMID 39071701, 2024). "Additionally, MTT assay and colony formation assays showed reduced growth of glioblastoma cells and suppressed formation of colonies in the absence of NUAK2." (PMID 40770117, 2025).
glioma (4 papers, 2021 to 2025). A benign or malignant brain and spinal cord tumor that arises from glial cells (astrocytes, oligodendrocytes, ependymal cells). "Defining these targets will be key to understanding NUAK2’s full oncogenic potential in glioma and other cancers." (PMID 40770117, 2025). "Taken together, these data suggest that ECM-related terms are significantly influenced by NUAK2 expression in both glioma cell lines and human GBM patients." (PMID 40770117, 2025). "Using this system, we conducted both Nuak2-GOF and -LOF studies to determine the role of Nuak2 in glioma formation." (PMID 40770117, 2025). "CRISPR-mediated deletion of NUAK2 in glioma cells attenuated proliferation and migration, while NUAK2 overexpression promotes these processes." (PMID 40770117, 2025). "We further assessed the selectivity of the inhibitor across four glioma cell lines, first confirming the inhibitor targets NUAK2 kinase activity in these cells." (PMID 40770117, 2025). "To determine if NUAK2 is sufficient to drive proliferation in glioma cells, we overexpressed NUAK2 via lentiviral transduction in the two glioma cell lines with low NUAK2 endogenous expression, U87 and LN229." (PMID 40770117, 2025). "To determine if NUAK2 can drive proliferation in proliferation in a glioma stem cell (GSC) context, we assessed the effects of NUAK2 overexpression in two low NUAK2-expressing GSC lines, GSC11 and GSC23." (PMID 40770117, 2025). "To further understand the mechanism of NUAK2 activity in glioma cells, we performed Kyoto Encyclopedia of Genes and Genomes (KEGG) pathway enrichment analysis on the U251-NUAK2-CR RNA-seq-derived DEGs to identify significantly dysregulated biological pathways." (PMID 40770117, 2025). "Together, these findings indicate that NUAK2 promotes proliferation and migration in glioma cell lines and GSCs, supporting its critical role in GBM progression." (PMID 40770117, 2025). "Roles for NUAK2 in several non-CNS cancers have been reported, with its expression being highly correlated with tumor progression and poor prognosis in patients." (PMID 40770117, 2025). "Since it was found that NUAK2 modulated glioma proliferation by inhibiting p27kip1, we detected the expression pattern of PCNA (a general marker of dividing cells) to determine the relationship between NUAK2 and the proliferation of SCs." (PMID 39071701, 2024). "Although we centered our analysis on NUAK2, NUAK1—its closely related kinase—has also been implicated in glioma progression, suggesting that both kinases may play complementary or distinct roles in disease pathogenesis." (PMID 40770117, 2025). "Finally, our data demonstrate that pharmacological inhibition of NUAK2 using HTH-02-006 suppresses growth across four glioma cell lines in both attached and suspension conditions." (PMID 40770117, 2025). "Importantly, pharmaceutical inhibition of NUAK2 exhibits significant effects in mitigating glioma progression." (PMID 40770117, 2025). "Among these oncogenes, overexpression of NUAK2 promotes proliferation and invasion of A172,GLI1 is a well-known glioma-associated transcription factor; suppression of TMEM140 attenuates growth of glioma cell." (PMID 35521558, 2022). "Additionally, analysis of the Chinese Glioma Genome Atlas (CGGA) databases and TCGA revealed a correlation between NUAK2 levels and glioma tumor grade, where high-grade gliomas exhibited greater NUAK2 expression than low-grade gliomas; implying that NUAK2 may play a role in brain tumor malignancy." (PMID 40770117, 2025). "NUAK2 mRNA levels in ovarian cancer are not related to a lower survival rate, whereas high NUAK2 expression in glioma patient samples decreases the survival rate from 13% to 6%, indicating poor prognosis." (PMID 34685740, 2021).
glioma (continued). "To examine their relationship more closely, we assessed their expression patterns across development and found that NUAK1 did not share the same dynamic expression pattern across development as NUAK2, nor did its expression correlate with glioma tumor grade or patient survival." (PMID 40770117, 2025).
acral melanomas (3 papers, 2011 to 2017). "High levels of expression of NUAK2 were found in patients with acral melanoma and are associated with increased risk of relapse." (PMID 24743024, 2014). "NUAK2 knockdown suppresses melanoma cell growth in vitro and tumorigenicity in vivo and has been proposed as a new oncogene in acral melanoma." (PMID 24743024, 2014). "Clinical data also suggest that NUAK2 plays a pivotal role in melanomagenesis in acral areas and has effects on the survival of patients with acral melanomas." (PMID 21911917, 2011). "Using the candidate gene approach, NUAK2 at this locus has been revealed as a promising gene that participates in the clinical outcome of acral melanomas." (PMID 21911917, 2011).
ovarian carcinoma (3 papers, 2011 to 2021). A malignant neoplasm originating from the surface ovarian epithelium. "Ourdata suggest that NUAK2 warrants further investigation inin vitro functional models of ovarian cancer pathogenesis." (PMID 21423607, 2011).
bladder cancer (2 papers, 2018 to 2024). "Moreover, in human patient samples, we show that NUAK2 expression is elevated in aggressive, high-grade bladder cancer and strongly correlates with a YAP/TAZ gene signature." (PMID 30158528, 2018). "In addition, we show that in human patient samples, NUAK2 expression is elevated in aggressive, high-grade (HG) bladder cancers and strongly correlates with a YAP/TAZ gene signature." (PMID 30158528, 2018). "NUAK2 is a YAP/TAZ target gene that promotes tumor progression in liver and bladder cancer, and CTGF, a well-established YAP/TAZ target gene, has clear roles in cancer." (PMID 38473214, 2024). "Thus, aggressive HG bladder cancers are characterized by elevated NUAK2 expression and YAP/TAZ activity, and either blocking expression or pharmacologically inhibiting NUAK2 is effective in restoring Hippo pathway activity and attenuating cell growth." (PMID 30158528, 2018).
cholangiocarcinoma (2 papers, 2018 to 2024). A carcinoma that arises from the intrahepatic biliary tree (intrahepatic cholangiocarcinoma) or from the junction, or adjacent to the junction, of the right and left hepatic ducts (hilar cholangiocarcinoma). "These enhancers were classified as super-enhancers in human cholangiocarcinoma and mesothelioma cell lines, arguing for the importance of NUAK2 in these cancers." (PMID 30446657, 2018). "Both YAP1 and TEAD were found to bind to NUAK2 super-enhancer regions in cholangiocarcinoma and mesothelioma cell lines, and acute overexpression of YAP1 upregulated NUAK2 mRNA and protein, while depletion of YAP1 or both YAP1 & TAZ each reduced NUAK2 expression." (PMID 38939918, 2024).
pancreas cancer (2 papers, 2021).
atherosclerosis (1 paper, 2024). A disease characterized by the build-up of fatty material and calcium deposition in the arterial wall resulting in partial or complete occlusion of the arterial lumen. "Together, this indicates an anti-inflammatory role for NUAK2 signaling in adipocytes and CD4+ T cells, but a study in the context of atherosclerosis is lacking so far." (PMID 38892400, 2024).
colitis (1 paper, 2022). Inflammation of the colon. "Here, we unravelled that the expression of GPR65 was enhanced in inflamed gut mucosa and PB‐CD4+ T cells of active IBD patients and identified that GPR65 could facilitate Th1 and Th17 cell differentiation and participate in the etiopathogenesis of colitis by impeding NUAK2 expression." (PMID 35343079, 2022).
colonic tumor (1 paper, 2018). "Further, heterozygous knockout NUAK2 mice are sensitized to azoxymethane-induced colonic tumor formation." (PMID 30446657, 2018).
gastric cancer (1 paper, 2025). A primary or metastatic malignant neoplasm involving the stomach. "Through its actions, OTUD7B promotes the progression of gastric cancer by enhancing the activity of the YAP1/NUAK2 axis." (PMID 39936032, 2025).
Hepatitis (1 paper, 2021). Inflammation of the liver. "The K81 methionine (M) and T208A NUAK2 mutants have been described to allow hepatitis C virus (HCV) replication, whereas the NUAK2 wild type (WT) impairs HCV replication in Huh 7.5.1 hepatitis cells." (PMID 34685740, 2021).
ischemia (1 paper, 2020). A hypoperfusion of the BLOOD through an organ or tissue caused by a PATHOLOGIC CONSTRICTION or obstruction of its BLOOD VESSELS, or an absence of BLOOD CIRCULATION. "Nuak2, also termed SNARK, has been identified as a mediator of insulin-independent glucose transport, specifically regulating exercise- and ischemia-stimulated glucose transport in the heart and contraction-stimulated glucose transport in skeletal muscle." (PMID 33105775, 2020).
liver fibrosis (1 paper, 2019). "Pathologically, NUAK2 regulates hepatitis C virus replication and enhances TGFβ signaling and hepatic fibrosis." (PMID 30622137, 2019). "The impact of NUAK2 on TGFβ signaling agrees with findings where NUAK2 enhances TGFβ signaling in hepatocytes infected with hepatitis C virus, thus promoting liver fibrosis." (PMID 30622137, 2019).
malignant glioma (1 paper, 2025). A grade III or grade IV glioma arising from the central nervous system. "Lastly, we determined that pharmaceutical inhibition of NUAK2 is sufficient to impede the proliferation and migration of malignant glioma cells." (PMID 40770117, 2025). "We found robust expression of NUAK2 in the embryonic brain that decreases throughout postnatal stages and then is re-expressed in malignant gliomas." (PMID 40770117, 2025). "Together with our results from orthotopic U251 transplants, these findings indicate that NUAK2 promotes tumorigenesis in in vivo models of high-grade glioma." (PMID 40770117, 2025). "Given the limitation that BALB/c nude mice are immunocompromised, we further examined the role of Nuak2 using a piggyBac in utero electroporation (PB-IUE) model of malignant glioma." (PMID 40770117, 2025). "Similarly, in an in vivo mouse model of malignant glioma, NUAK2 deletion suppressed tumor growth, and NUAK2 overexpression promoted tumor growth." (PMID 40770117, 2025). "Modulation of NUAK2 expression in in vivo models of malignant glioma mimics these results." (PMID 40770117, 2025).
prostate carcinoma (1 paper, 2025). A carcinoma that arises from epithelial cells of the prostate gland. "Researchers observed that targeting NUAK2 in vitro resulted in reduced proliferation, diminished growth of three-dimensional tumor spheroids, and decreased Matrigel invasion by prostate cancer cells." (PMID 39936032, 2025). "NUAK2 expression levels are raised in prostate cancer and metastatic castration-resistant prostate cancer (mCRPC) relative to normal tissue, with elevated expression correlating with an increased risk of metastasis." (PMID 39936032, 2025).
renal cell carcinoma (1 paper, 2021). "The K82 arginine (R) mutant is an inactive NUAK2 mutant, due to its interference with the NUAK2 autophosphorylation site inhibiting its anti-apoptotic activity in the ACHN renal cell carcinoma cell line." (PMID 34685740, 2021).
serous carcinoma (1 paper, 2011). "Weconfirmed protein expression of NUAK2 in normal ovarian tissue and analysed theexpression of NUAK2 in serous carcinoma, Cohorts 1 and 2, which comprised 20whole sections and 96 cases on a tissue microarray, respectively." (PMID 21423607, 2011).
serous ovarian cancer (1 paper, 2011). "NUAK2, upregulated in ovarian surfaceepithelium in proestrus and predicted to have a driver mutation in ovariancancer, was examined in a larger cohort of serous ovarian cancer where patientswith lower NUAK2 expression had shorter overall survival." (PMID 21423607, 2011).
spina bifida (1 paper, 2024). A congenital neural tube defect in which vertebrae are not fully formed. "Furthermore, NUAK2 has been reported to function in neural tube regeneration, with NUAK2 knockout mice display spina bifida, exencephaly, and facial clefting." (PMID 39071701, 2024).
Spinal dysraphism (1 paper, 2025). A heterogeneous group of congenital spinal anomalies that result from defective closure of the neural tube early in fetal life. "This is the first report of spinal dysraphism segregating in a family with a monoallelic variant in NUAK2." (PMID 41008661, 2025).
thyroid cancer (1 paper, 2024). "The results showed that eight key genes (NUAK2, TNFRSF10B, TNFRSF10C, TNFRSF12A, UNC5B, and PMAIP1) exhibited good diagnostic performance in differentiating between thyroid cancer patients and controls." (PMID 39104814, 2024). "TNFRSF10B, TNFRSF10C, TNFRSF12A, UNC5B, PMAIP1, and IL18 had increased expression in thyroid cancer tissues, while NUAK2 was decreased." (PMID 39104814, 2024).
tumor (23 papers, 2011 to 2025). "NUAK2 is associated with melanoma tumor growth, both by controlling cell cycle progression via cyclin-dependent kinase 2 (CDK2), as well as by regulating migration." (PMID 34282782, 2021). "NUAK1 (NUAK family SnF1-like kinase-1) and NUAK2 protein kinases are activated by the LKB1 tumour suppressor and have been implicated in regulating multiple processes such as cell survival, senescence, adhesion and polarity." (PMID 24785407, 2014). "The putative drivermutation in NUAK2 and association of loss of expression withreduced overall survival suggests NUAK2 may have tumour suppressive activity." (PMID 21423607, 2011). "Histological analysis further confirmed that tumor sizes were markedly smaller in the NUAK2-CR cohort, with notably fewer Ki67 and PCNA-expressing cells." (PMID 40770117, 2025). "Together, these findings classify Nuak2 as a fetal oncogene in both humans and mice, and demonstrate its strong association with GBM prognosis and tumor progression." (PMID 40770117, 2025). "Survival studies revealed that the Nuak2-CR cohort had significantly prolonged 50% survival rates compared to control tumor-bearing mice." (PMID 40770117, 2025). "Our results showed an increase in CD-44 positive staining in Nuak2-OE tumors compared to control tumor-bearing mice, while Nuak2-CR tumors had significantly fewer Ki67, PCNA, and CD-44 positive cells." (PMID 40770117, 2025). "Together with our gene expression analysis, these findings suggest that NUAK2 functions as a fetal oncogene and demonstrates an explicit relationship between tumor progression and NUAK2 expression in GBM." (PMID 40770117, 2025). "On the other hand, hsa‐miR‐195‐5p is responsible for NUAK2 gene expression level alteration and plays a crucial role in tumor progression." (PMID 38717954, 2024). "Separate extracts of tumor cells from patients with high-grade and low-grade BC were tested and showed that NUAK2 expression in tumor cells was significantly higher in high-grade patients than in low-grade patients." (PMID 35912245, 2022). "It has also been observed that, among YAP-positive malignancies, targeting α2β1 integrin and NUAK family kinase 2 (NUAK2) expression blocks tumor progression by inhibiting the MST-YAP cascade and actin-myosin activity." (PMID 36033517, 2022). "Clearly, these investigations point out the possibility of a major role of the NUAK1 and NUAK2 protein kinases in tumor development and support their potential role as novel therapeutic targets." (PMID 34685740, 2021). "Despite recently accumulated evidence, only limited data are available regarding NUAK1 and NUAK2 and their role in cellular physiology, their potential downstream targets in various tissues, and how gene amplifications affect tumor development." (PMID 34685740, 2021). "In this manner, determining the regulatory network that involves NUAK1 and NUAK2 in tumor development is important." (PMID 34685740, 2021). "In parallel, analysis of tumor growth in vivo, using an orthotopic mouse mammary model, revealed robust tumor growth between 1 and 4 weeks in controls, whereas NUAK2 KOs displayed reduced tumor volume increases." (PMID 30158528, 2018). "Staining of sections revealed a dramatic reduction in the levels of YAP/TAZ in the NUAK2 KO tumor cells consistent with our observations in cell-based assays." (PMID 30158528, 2018). "Nuclear YAP/TAZ drives cancer progression; thus, we next examined the contribution of NUAK2 to cell growth or tumor formation." (PMID 30158528, 2018).